SOX9 (SRY-box transcription factor 9)
Diseases named in the same sentence as SOX9 in open-access papers (continued):
Sharing a sentence is not in itself a finding about the gene and the disease.
breast carcinoma (continued). "MiR-133b played tumor suppressing roles in several malignancies through regulating in gastric cancer, targeting Sox9 in breast cancer, negatively regulating EMP2 in glioma, targeting methyltransferase DOT1L in colorectal cancer, and targeting EGFR in esophageal squamous cell carcinoma." (PMID 33816233, 2021). "Consistent with our TCGA analysis and murine data, we observed that 43% of TNBC cores were Sox10hi and that all Sox10hi nuclei in those cores also showed a pSox9 S181hi signal, suggesting that the activation of Sox9 and Sox10 induction is also observed in human breast cancer samples." (PMID 33985544, 2021). "In addition, extracellular ATP promotes the invasion and chemoresistance of breast cancer cells through the sex-determining region Y-box 9 (SOX9) signaling pathway, which interacts with IL-6–Janus kinase 1–STAT3 signaling." (PMID 34638242, 2021). "We repeated our analysis in another mammary tumor type (PyMT), with Sox9 marking the CSCs." (PMID 34911937, 2021). "Interestingly, analysis of murine and human mammary tumors reveals a direct correlation between the levels of active phospho-Sox9 S181 and Sox10 expression." (PMID 33985544, 2021). "More importantly, SOX9 was inversely associated with estrogen receptor (ER) and progesterone receptor (PR) status, suggesting that SOX9 might be highly positive in HR- breast cancer." (PMID 32398735, 2020). "If Sox10 and Sox9 have discrete functions within basal or luminal progenitors in the normal gland, they may also have discrete functions in breast cancer subtypes that differ in their contributions of basal and luminal cells." (PMID 33082503, 2020). "To seek potential biomarkers of THZ1 sensitivity, we re-analyzed the mRNAs profile in breast cancer cells treated with THZ1 from the previous study and demonstrated that elevated expression of SOX9 was significantly associated with the sensitivity of THZ1 in TNBC." (PMID 32398735, 2020). "Moreover, based on the tissue array of 278 patients and over 900 samples from TCGA data, we found that SOX9 expression was significantly higher in TNBC than HR+ breast cancers." (PMID 32398735, 2020). "This is may be partly due to the observed estrogen-dependent reduction of Sox9 expression in breast cancer cells." (PMID 30622340, 2019). "Knockout of Sox9 mimicked the inhibitory impact of miR‐215‐5p on breast carcinoma cells." (PMID 31538724, 2019). "We performed luciferase reporter tests to show that SRY‐Box 9 (Sox9) is the target of miR‐215‐5p; as predicted, Sox9 depletion replicates the suppressive effects of miR‐215‐5p on breast carcinoma cells, and overexpression of Sox9 rescues the effects of miR‐215‐5p on breast cancer cell progression." (PMID 31538724, 2019). "Sry-related high motility group box 9 (SOX9) plays active roles during tumorigenesis and progression in various types of human cancers and was reported to be upregulated in tamoxifen-resistant breast cancer and to drive breast cancer endocrine resistance." (PMID 31624470, 2019). "Our study has revealed that NAC dramatically alters epigenetic heterogeneity in breast cancer and induces convergent hypomethylation of stem cell quiescence-associated genes, ALDH1L1, HOPX, WNT5A and SOX9, which can potentially be developed as therapeutic targets or biomarkers for chemoresistance." (PMID 30774927, 2019). "Accordingly, as we speculated, miR‐215‐5p mediated the progression of breast cancer cells via regulating Sox9." (PMID 31538724, 2019). "Thus, HDAC5 and SOX9 expression levels are crucial factors related to the overall survival in endocrine-therapy-treated ER+ breast cancer." (PMID 31690832, 2019). "However, the correlation between SOX9 acetylation level and overall survival of tamoxifen-resistance breast cancer patients still needs more clinical evidence." (PMID 31690832, 2019).
breast carcinoma (continued). "Sox9 is a poor prognostic indicator and is strongly associated with Wnt signaling via LRP6 (Low-density lipoprotein receptor-related protein 6) and TCF4 (Transcription Factor 4) in breast cancer." (PMID 31394796, 2019). "SOX9 is an important transcription factor that confers CSC phenotype in breast cancer." (PMID 31690832, 2019). "Targeting C-MYC/HDAC5/SOX9 axis might be beneficial for the discovery of new strategies for ER+ breast cancer therapy." (PMID 31690832, 2019). "Furthermore, we investigated the effect of knocked‐down Sox9 on the aggressiveness of breast carcinoma cells." (PMID 31538724, 2019). "Moreover, analysis of an online database (GSE52327) that compared the expression profiles of ALDH− and ALDH+ cell populations isolated from breast cancer samples, also showed higher SOX9 mRNA levels in ALDH+ than in ALDH− cells." (PMID 30622340, 2019). "Sox9 is elevated in breast cancer patients after endocrine therapy failure." (PMID 30622340, 2019). "On the basis of the inverse correlation observed between Sox9 and ER expression, we hypothesized that Sox9 expression may be regulated by estrogen in breast cancer cells." (PMID 30622340, 2019). "In addition, miR‐215‐5p is a suppressive miRNA in the progression of breast cancer by regulation of Sox9 expression." (PMID 31538724, 2019). "Moreover, gene expression profiling has identified breast cancer subtypes, including an aggressive basal-like (BL) subtype and Sox9 is one of the signature genes that define the BL subgroup of breast cancer." (PMID 29970901, 2018). "In vitro studies could show that SOX9 is also a marker of cancer stem cells in breast cancer and other tumour entities." (PMID 29121666, 2017). "Finally, we identified SOX9 as an HDAC9 target gene in breast cancer cells which supports, at least partly, its mitogenic activity." (PMID 26930713, 2016). "In both breast cancer and glioma, Sox9 facilitates Wnt/β-catenin signaling." (PMID 27105493, 2016). "Moreover, SOX9, which is a Wnt-target in intestinal crypts, is also highly expressed in basal-like breast cancers." (PMID 27420097, 2016). "Finally, in a large panel of breast cancer biopsies, HDAC9 expression was significantly increased in tumors of the basal subtype, correlated with SOX9 expression and associated with poor prognosis." (PMID 26930713, 2016). "We found a strong increase in the expression of SNAI2 (∼73-fold) and SOX9 (∼67-fold) which may both contribute to the maintenance of human breast cancer stem cell phenotype." (PMID 24498388, 2014). "Sox9, a nuclear TF, is often localized in cytoplasm of invasive and metastatic breast cancer." (PMID 24404438, 2013). "Expression of Sox9, Sox10 and Slug was seen in 82-96% of the tumor cells prior to chemotherapy in our study, further supporting the fact that the transcription factors are highly active in the breast cancer tissue." (PMID 24404438, 2013). "Recent cogent evidence has provided a link between SOX9 and cancer development and progression, and the upregulation of SOX9 has been observed in several types of solid tumors, including lung adenocarcinoma, breast carcinoma, colorectal cancer, and prostate cancer." (PMID 22385677, 2012). "SOX9 has been shown to be relevant at distinguishing mesenchymal chondrosarcoma from other small blue round cell tumours and at modulating retinoid-mediated growth in breast cancer cells." (PMID 18087279, 2008). "Additionally, miR-133 modulates breast cancer tumorigenesis and metastasis via targeting SOX9." (PMID 41230330, 2025). "Indeed, SOX9 constitutes an important regulator of breast cancer survival and metastasis." (PMID 39706842, 2024). "Therefore, MEG8 could be the link of senescence, aging and breast cancer, and this effect could be mediated by SOX9." (PMID 39706842, 2024).
breast carcinoma (continued). "Considering their suppressive effects on expression of SOX9 as master regulator of cell fate in breast cancer and their inhibitory impact on the breast cancer cell viability, miR-224-3p and miR-134-3p could be considered as potential tumor-suppressive miRNAs in breast cancer." (PMID 35779228, 2023). "Therefore, C-MYC/HDAC5/SOX9 axis is essential for promoting tamoxifen resistance in breast cancer." (PMID 31690832, 2019). "Finally, Sox9 expression is required for Wnt signalling in breast cancer cells." (PMID 30622340, 2019). "Thus, SOX9 expression in carcinogenesis and malignity in breast cancer tumors is relevant." (PMID 31057614, 2019). "Taken together, our results showed that overexpression of ZEB1 could transcriptionally suppress the expression of ERα and miR-190 and led to SOX9 elevation and activation of Wnt/β-catenin signaling, resulting in anti-estrogen resistance therapies in breast cancer." (PMID 30658681, 2019). "This could also be shown in our study and not surprisingly SOX9 positivity was also associated with shorter relapse free survival in patients with breast cancer." (PMID 29121666, 2017). "With emerging evidence that Sox9 may contribute to maintenance of breast cancer stem cells, the inducible Sox9 deletion model and the insights presented here should facilitate future efforts to validate Sox9 as a biomarker or therapeutic target in breast cancer." (PMID 25527186, 2014). "SOX9, acting as a downstream factor of SOX2, contributes to tamoxifen resistance by regulating ALDH1A3 expression and modulating Wnt signaling in breast cancer." (PMID 40240356, 2025). "Another study has reported that SOX9 is involved in ATP-driven invasion and chemoresistance by targeting CEACAM5/6, ABCB1, and ABCG2 in breast cancer." (PMID 40240356, 2025). "Following chemotherapy for breast cancer, ONECUT2 induces tumor stemness and triggers the expression of stem cell-related genes, including SOX9, SOX2, and NOTCH1, thereby contributing to chemoresistance." (PMID 38997271, 2024). "The modulating effects of miR-134-3p, miR-224-3p, and miR-6859-3p on SOX9 expression were analyzed by qPCR and Western blot in human MDA-MB-231 breast cancer cells." (PMID 35779228, 2023). "GWAS that implicate BNC2-associated alleles with adolescent idiopathic scoliosis also implicate other ECM-associated genes and cytokines that we also find to be under BNC2 control in our breast cancer system (MATN1, MMP9, SOX9, IL-6 as examples)." (PMID 37536977, 2023). "Sox9 has been shown to mediate the Wnt/β-catenin activation through the regulation of LRP6 and TCF4 expression in breast cancer." (PMID 34615853, 2021). "Tamoxifen is a first-line treatment for breast cancer, HDAC5 deacethylated SOX9 and made it localized in the nucleus, which was responsible for tamoxifen resistant in breast cancer." (PMID 34178647, 2021). "This suggests that SOX9 and SOX10 are likely to act cooperatively to regulate cell fate plasticity in mammary stem/progenitor cells and breast cancer progression." (PMID 32521267, 2020). "In contrast, a markedly increased Sox9 expression, but rather low expression levels of Snail and Slug were observed in MDA-MB-231-Hyg breast cancer cells." (PMID 32430004, 2020). "The results showed that SOX9 was localised to the nucleus in ER+ MCF-7 breast cancer cells but to the cytoplasm in ER– MDA-MB-231 breast cancer cells, suggesting that the localisation of SOX9 might be associated with different functions in ER+ or ER– breast cancer." (PMID 31690832, 2019). "In breast cancer, primary tumors that exhibit high expression levels of both SLUG and SOX9 had a significantly lower overall survival rate than the rest of the patients." (PMID 31057614, 2019). "As SOX9 has distinct subcellular localisation in different types of breast cancer, so we first verified the localisation of SOX9 in ER-positive (MCF-7) and ER-negative (MDA-MB-231) breast cancer cells." (PMID 31690832, 2019).
breast carcinoma (continued). "To further demonstrate that miR-190 mediates the regulation of SOX9 expression via ERα and ZEB1 in breast cancer cells, we transfected ERα plasmid into MDA-MB-231 cells in addition to E2 stimulation." (PMID 30658681, 2019). "Inhibition of Sox9 reduced tumorigenicity and E CSC population, and sensitized breast cancer cells to therapeutic intervention." (PMID 31394796, 2019). "In accordance with the dual CK5 and CK14 expression, all hybrid clone cells also revealed a co-expression of SOX9 and SLUG, which cooperatively determine the stem cell state of normal human mammary cells and human breast cancer cells." (PMID 28768501, 2017). "Altogether these results demonstrate that the SOX9 gene is an HDAC9 target gene, which controls its mitogenic effect in breast cancer cells." (PMID 26930713, 2016). "So far, the direct validated targets of this miRNA include stem cell self-renewal regulator SOX2 in breast cancer, TGFBR1 and FGF9 in hepatocellular carcinoma, SOX9 and ALDH1 in ductal carcinoma in situ and IGF1R in lung cancer." (PMID 26882564, 2016). "SOX9 is also correlated with Wnt/b-catenin activation, which induces increased LRP6 and TCF4 expression in breast cancer." (PMID 26009899, 2015). "Sox9 cooperates with Slug to induce EMT in mammary stem cells, and tumor progression in breast cancer." (PMID 25004243, 2014). "Cluster I showed overexpression of the lncRNAs that influence their neighboring genes, ALDH1A3 (a breast cancer stem cell marker), SOX4, SOX9, and VIM." (PMID 25296969, 2014). "SOX9 is a mark for adult human progenitor cells, mediates deposition of ECM component and is a major transcriptional regulator of mitotic activity in breast cancer." (PMID 23077491, 2012). "Additionally, we found that breast cancer cells that overexpress MEG8 have decreased the expression levels of some stem cell markers such as BMI1, SOX9 and KLF4 and in some cases also NANOG or SOX2, but not OCT4." (PMID 39706842, 2024). "We observed that SOX2 and OCT4 expression was significantly increased in tbLCM-treated breast cancer cells as compared to tnLCM or BM treated cells, while expression of SOX9 and NANOG was not different between treatment conditions." (PMID 38581619, 2024). "Besides, JAK1-STAT3 pathway up-regulated the expression of SOX9 and induced CEACAM5 overexpression, thus promoting breast cancer cell invasion." (PMID 38686388, 2024). "Notably, SOX9 is highly expressed together with SOX4, 6, 8, 10 and 11 in triple-negative breast cancer, representing the breast cancer subtype with worst prognosis." (PMID 35779228, 2023). "To determine, whether direct binding of miR-134-3p, miR-224-3p, and miR-6859-3p to the SOX9 3′-UTR was cell line independent, we repeated the luciferase assay with an additional breast cancer cell line, MCF-7 and with human embryonic kidney cells (HEK 293)." (PMID 35779228, 2023). "Although miR-6859-3p had the lowest impact on SOX9 expression, this miRNA showed inhibitory effects in reporter assays in both breast cancer cell lines tested, but not in HEK293 cells." (PMID 35779228, 2023). "Importantly, we also recapitulated the interaction between SLUG/SOX9 and NELF-E in another breast cancer cell line, BT-549, that expresses endogenous levels of SOX9 and SLUG, highlighting the generality of our findings." (PMID 37117180, 2023). "Among them, linc02095 induces SOX9 transcription in breast cancer cells by recruiting PolII and raising H3K4me3 levels, which contributes to revealing the mechanism by which SDNOR regulates the expression and transcriptional activity of SOX9." (PMID 37107173, 2023). "Altogether, these results indicated that Sox9+ luminal cells can serve as cells of origin for basal-like carcinomas driven by LATS1/2 deletion, reinforcing the implication of this lineage as an origin for basal-like breast cancers." (PMID 36443313, 2022).
breast carcinoma (continued). "Although it has been demonstrated that miR-133b is down-regulated in breast cancer and suppresses tumorigenesis and metastasis by targeting Sox9, the reason for miR-133b dysregulation has not been clearly illustrated." (PMID 31344855, 2019). "Interestingly, latency competent breast cancer cells (LCBCC, cancer cells that can reseed organs with latent metastasis) have been found to maintain a stem cell-like state and express Sox2 and Sox9 transcription factors." (PMID 31394796, 2019). "SOX9 enhanced TCF4 transcription and Wnt/β-catenin signaling in breast cancer." (PMID 27420097, 2016). "Finally, we identified the SOX9 gene as a new HDAC9 target gene which explained, at least partly, the effect of HDAC9 on breast cancer cell proliferation." (PMID 26930713, 2016). "Strong stromal Sox9 expression in breast cancer after chemotherapy was found to bear negative prognostic information and was associated with shortened overall survival." (PMID 24404438, 2013). "In summary, our study shows, that strong stromal SOX9 expression in breast cancer after neoadjuvant chemotherapy bears negative prognostic information and is associated with shortened overall survival." (PMID 24404438, 2013). "In oncology, SOX9 promotes tumor persistence, drug resistance, and immune evasion through key pathways such as PI3K/AKT, Wnt/β-catenin, and TGFβ/Smad, particularly in gastric, liver, and breast cancers, where it supports cell dormancy and helps evade NK cell surveillance." (PMID 41293317, 2025). "We believe tuft cell-like properties, particularly those related to POU2F3 and SOX9, in neoplastic and non-neoplastic breast tissues are worth further investigation and may be key to dissecting the complex biology of breast cancers, particularly TNBCs." (PMID 37179317, 2023). "Moreover, it would be interesting to investigate whether the same cross-talk between SOX9 and RIP140 also occurs in other types of cancer, including breast cancer." (PMID 34206767, 2021). "In addition, MES TFs, SMAD3, SOX9, WWTR1, and IFI16 had 32, 23, 6, and 5 connections, respectively, and KEGG gene enrichment analysis revealed enrichment for ‘breast cancer’, ‘prostate cancer’, and ‘hepatocellular carcinoma’ processes in addition to ‘miRNA in cancer’ terms." (PMID 35201514, 2021). "Interestingly, SOX9 displays strong nuclear localization in highly invasive triple-negative breast cancer cells as opposed to other breast cancer subtypes." (PMID 32957640, 2020). "Likewise, knockdown of either Slug or Sox9 greatly inhibited the tumor-initiating ability of MDA-MB-231 breast cancer cells, whereas usually non-metastatic MCF7ras breast cancer cells became highly metastatic when Slug and Sox9 were co-expressed." (PMID 32430004, 2020). "Studies have indicated that miR-133b can regulate oncogenic transcripts of gastric, esophageal, or breast cancer by targeting Fascin Actin-Bundling Protein 1(FSCIN1)/Sp1, the epidermal growth factor receptor (EGFR) and SRY-Box Transcription Factor 9 (SOX9), respectively." (PMID 31771219, 2019). "Moreover, coexpression of SLUG and SOX9 in nonmetastatic breast cancer cells induces EMT and macrometastasis formation." (PMID 29853913, 2018). "In order to define whether SOX9 mediated the mitogenic effect of HDAC9 in breast cancer cells, we modulated SOX9 gene expression in MCF7 cells overexpressing or not HDAC9." (PMID 26930713, 2016). "Moreover, assessment of breast cancer stem or luminal progenitor cell biomarkers showed positivity in most LAM tissue for the aldehyde dehydrogenase 1 (ALDH1), integrin-ß3 (ITGB3/CD61), and/or the sex-determining region Y-box 9 (SOX9) proteins." (PMID 26167915, 2015). "Hence, SOX9 may be involved in MDA-MB-231 cells proliferation and downregulation of its expression and/or phosphorylation may contribute to the inhibitory effects of Fx and Fxol on viability of estrogen resistant breast cancers." (PMID 26264004, 2015).